EGFR (epidermal growth factor receptor)
Diseases named in the same sentence as EGFR in open-access papers (continued):
Sharing a sentence is not in itself a finding about the gene and the disease.
lung adenocarcinoma (continued). "In early-stage lung adenocarcinoma, EGFR mutation may be considered as a treatment response predictor for tyrosine kinase inhibitors, instead of a predictor of clinical prognosis." (PMID 36766495, 2023). "Hence, the current study aims to assess the relationship between EGFR mutations and smoking patterns among patients diagnosed with lung adenocarcinoma referred to pathological laboratories." (PMID 37425232, 2023). "Moreover, the synergistic effect of gefitinib and BYL719 was also confirmed in the 3D cell culture model, the in vivo model, as well as in the organoid model from a lung adenocarcinoma patient with EGFR, ErbB2, PIK3CA mutations and MET amplification." (PMID 37553597, 2023). "Remarkably, the patients in the GSE31210 cohorts showed a higher EGFR mutation rate (61%) compared to the TCGA cohort (11%), which is consistent with the Asians with higher EGFR mutation rates in lung adenocarcinoma such as the GSE31210 cohort conducted in Japan." (PMID 36768704, 2023). "Together, our results may provide important information in predicting EGFR mutation status, EGFR subtypes and OS, to help lung adenocarcinoma treatment and prognosis." (PMID 37223682, 2023). "Therefore, we evaluated the relationship between FDG PET texture indices and the EGFR mutation status in patients with newly diagnosed lung adenocarcinoma." (PMID 37185611, 2023). "Our study aimed to investigate the potential of a time-variable radiomics signatures derived from time-serial CT scans to accurately predict progression-free survival (PFS) and stratify the risk of acquired resistance in lung adenocarcinoma patients undergoing EGFR-TKI treatment." (PMID 37958300, 2023). "In addition, we detected the synergistic effect of gefitinib and BYL719 in organoids derived from a lung adenocarcinoma patient, harboring EGFR (L838V, L861Q), PIK3CA (H1047L), ErbB2 (D871N) mutations and MET amplification." (PMID 37553597, 2023). "Therefore, genetically mutated EGFR is an important target for targeted therapy in lung adenocarcinoma." (PMID 36744262, 2023). "Another study from China showed that in first-line treatment of patients with advanced lung adenocarcinoma with uncommon EGFR mutations, the PFS was better with first-generation EGFR-TKIs than with platinum-based chemotherapy, but the OS was inferior to chemotherapy." (PMID 37366888, 2023). "The OS of the patients was significantly prolonged as compared to those reported in previous studies, indicating that thoracic radiotherapy could significantly improve the prognosis of lung adenocarcinoma patients with EGFR mutation." (PMID 36070068, 2023). "Herein, we reviewed the progress in applying 18F-FDG PET/CT and radiomics in lung adenocarcinoma clinical research and how these data are analyzed via traditional statistics, machine learning, and deep learning to predict EGFR mutation status, all of which achieved satisfactory results." (PMID 38094613, 2023). "In this work, we first propose a radiogenomic workflow to characterize lung adenocarcinoma cases with respect to KRAS and EGFR mutational status using radiomic features extracted from the computed tomography (CT) images of patients affected by lung adenocarcinoma." (PMID 37508774, 2023). "Only one study found that eNOS 894 G/T variants were significantly associated with EGFR mutation types of lung adenocarcinoma, specifically exon 19 in-frame deletion and that this could be used to predict tumor invasiveness and response to therapy." (PMID 38107574, 2023). "Therefore, the combination test will reduce the total cost of molecular profiling, at least in Japan, if used for lung adenocarcinoma patients, in which the frequency of the EGFR mutation is approximately 30% or higher." (PMID 37174112, 2023). "In advanced lung adenocarcinoma patients with EGFR 19Del/21L858R mutations, the EGFR mutation abundance may be associated with the outcome when the patients were treated with EGFR-TKIs." (PMID 37658352, 2023).
lung adenocarcinoma (continued). "Thus, we present the case of a 65-year-old Caucasian male lung adenocarcinoma patient with an EGFR Exon 18 p.Glu709_Thr710delinsAsp mutation of uncertain therapeutic relevance." (PMID 37655099, 2023). "Furthermore, 54 DEGs were found to be implicated in various progression stages of lung adenocarcinoma, while 41 and 46 DEGs were found to be different according to the EGFR or KRAS mutation status of the tumor, respectively." (PMID 36832225, 2023). "All these clinicopathological features might represent a more locally invasive pattern of the EGFR mutation group in early-stage lung adenocarcinoma." (PMID 36766495, 2023). "Therefore, combination therapies have been suggested as a first-line therapeutic option for advanced lung adenocarcinoma patients with EGFR mutations." (PMID 37854677, 2023). "In conclusion, we developed and interpreted two optimal predictive models to identify EGFR mutation status and subtypes in patients with lung adenocarcinoma based on cross-combination method and XAI technology, and further constructed a prognostic model to predict their clinical outcome." (PMID 37223682, 2023). "Epidermal growth factor receptor (EGFR) gene mutations are the most prevalent oncogenic driver alteration among Asian patients with lung adenocarcinoma and may be present in up to 51.4% of patients." (PMID 37723837, 2023). "Based on the preliminary results of this study in a small patient population, FDG PET texture indices may be potential imaging biomarkers for the EGFR mutation status in patients with newly diagnosed lung adenocarcinoma." (PMID 37185611, 2023). "This study investigated the association of contrast-enhanced Computed Tomography (CT) radiomic features of lung adenocarcinoma lesions, alone or integrated with clinical parameters, with tumor mutational status (EGFR, KRAS, ALK alterations) and Overall Survival (OS)." (PMID 37760521, 2023). "These proteins may play important roles in the malignant progression of EGFR mutation‐positive lung adenocarcinoma." (PMID 37004157, 2023). "In addition, the presence of mutated EGFR-L858R is related to the invasive capacity of lung adenocarcinomas that present this mutation and is associated with malignant pleural effusion, as demonstrated in our patient." (PMID 37371673, 2023). "In stage I and stage II operable lung adenocarcinoma, our findings suggest that EGFR mutations may be considered as a treatment response predictor for TKI, and may not be a predictor of clinical prognosis." (PMID 36766495, 2023). "In EGFR-mutated lung adenocarcinoma, miR-502-3p was found to be upregulated." (PMID 37111289, 2023). "Tumor heterogeneity across patients is a plausible explanation for this observation: although there are certainly frequently mutated driver genes in lung adenocarcinoma, such as EGFR, KRAS or STK11, only a minority of patients’ tumor is found positive for each of these mutations." (PMID 37938580, 2023). "This article aims to use machine learning methods to construct a radiomics model based on 18F-FDG PET/CT images to predict the EGFR mutation status in lung adenocarcinoma patients and evaluate the added value of clinical parameters in improving the predictive performance of the radiomics model." (PMID 37014500, 2023). "Therefore, identifying EGFR mutation status and subtypes are important for the treatment of patients with lung adenocarcinoma." (PMID 37223682, 2023). "Moreover, a previous study revealed that EGFR mutations, especially L858R mutations, increased the cell invasion ability in lung adenocarcinoma." (PMID 38067382, 2023).
lung adenocarcinoma (continued). "Also, our previous study has shown that machine learning model based on PET/CT handcrafted radiomics features (HRFs) achieved a good prediction performance in the identification of EGFR mutation status and subtypes in lung adenocarcinoma." (PMID 37223682, 2023). "L858R/L833V is a rare compound mutation found in 6% of lung adenocarcinoma EGFR mutation cases." (PMID 36923435, 2023). "The clinical stage could affect the model’s prediction performance, and the PET/CT joint model was more effective in predicting the EGFR mutation status in patients with advanced lung adenocarcinoma." (PMID 37014500, 2023). "Rare point EGFR mutations in exon 20 have been also identified in the C796 residue such as the G796R (0.56% of patients with lung adenocarcinoma treated with osimertinib), G796S, and G796D mutations, which are adjacent to C797 in exon 20 and can sterically impair the binding of osimertinib to EGFR." (PMID 37376053, 2023). "In contrast, one study in lung adenocarcinoma reported that OPN could cause EGFR phosphorylation, leading to sensitization to EGFR inhibitors." (PMID 37444590, 2023). "Myeloid cells are abundant in EGFR-mutated lung adenocarcinomas." (PMID 36672698, 2023). "Similarly, the correlation among oncogenic mutations in ROS1, ALK, EGFR and PD-L1 had been reported in lung adenocarcinoma." (PMID 36874015, 2023). "Histological study of the lung tissue showed lung adenocarcinoma with the EGFR L858R mutation." (PMID 37860534, 2023). "Since different EGFR mutation subtypes may have different biological behavioral functions, we further analyzed the differences in MMP11 expression levels in different EGFR mutation subtypes of lung adenocarcinoma." (PMID 36756152, 2023). "Hence, we would like to discuss Osimertinib as a viable treatment option in EGFR Exon 18 p.Glu709_Thr710delinsAsp mutated lung adenocarcinoma." (PMID 37655099, 2023). "Our model’s performance as evaluated on validation sets reflecting the real-world prevalence of EGFR mutations in lung adenocarcinoma suggests utility as a rule-out screening tool that could provide rapid genomic insights regarding a patient specimen." (PMID 36927889, 2023). "Furthermore, the possibility of EGFR mutation in lung adenocarcinoma patients with the ACE1 rs4646994 DD genotype was lower than that of II or ID genotype carriers." (PMID 37371643, 2023). "Furthermore, for patients with EGFR mutation-positive lung adenocarcinoma who developed acquired resistance to erlotinib or gefitinib, drug efficacy to the original TKI can be recovered when combining with conventional chemotherapy." (PMID 36910653, 2023). "As a local treatment, thoracic radiotherapy could improve the disease conditions of advanced lung adenocarcinoma patients with EGFR mutation." (PMID 36070068, 2023). "We report the case of a 79-year-old man who was diagnosed with epidermal growth factor receptor (EGFR) mutation positive lung adenocarcinoma (T2aN0M0, stage IB, EGFR exon 19 deletion), and was positive for anti-aminoacyl-tRNA synthetase antibodies with interstitial pneumonia." (PMID 38156131, 2023). "An example of a case where SL-SRS might be considered could include a patient with lung adenocarcinoma with a standard L858R epidermal growth factor receptor (EGFR) mutation with multiple brain metastases of varying sizes and locations." (PMID 37859877, 2023). "In Asian patients with lung adenocarcinoma, the EGFR mutation rate is as high as 50%." (PMID 37014500, 2023). "Therefore, the National Comprehensive Cancer Network guidelines recommend routine detection of EGFR mutations to guide molecularly targeted therapy for lung adenocarcinoma patients." (PMID 37749461, 2023). "Then, we included clinical parameters to construct joint models and evaluate whether adding clinical parameters can further improve the model performance in predicting EGFR mutation in lung adenocarcinoma patients with different clinical stages." (PMID 37014500, 2023).
lung adenocarcinoma (continued). "He had a history of lung adenocarcinoma with epidermal growth factor receptor (EGFR) mutation." (PMID 36320789, 2022). "The radiological features have been shown to reflect EGFR mutation status in lung adenocarcinoma." (PMID 35574401, 2022). "EMT may underlie phenotypic changes in EGFR-mutated lung adenocarcinomas treated with TKIs, although this has mostly been demonstrated in in vitro or cell-line studies and, rarely, in clinical settings, based mostly on case series or case reports." (PMID 35456982, 2022). "Our results indicated that radiomics alone could achieve a similar efficiency as clinical factors did in predicting acquired T790M mutation in advanced lung adenocarcinoma patients with progression on first- or second-generation EGFR TKIs." (PMID 35875167, 2022). "EGFR/ERBB1 is mainly associated with lung adenocarcinoma and squamous cell carcinoma development." (PMID 35903358, 2022). "Furthermore, Asian patients with lung adenocarcinoma have a high prevalence of epidermal growth factor receptor (EGFR) mutation (50%)." (PMID 36076157, 2022). "This was confirmed by numerous reports from frequently assessed populations, showing a huge variability of EGFR mutation frequencies in patients with lung adenocarcinoma, ranging between 6 and 41% in Europe, 3 and 42% in North America, and 20 and 76% in Asia-Pacific." (PMID 36011410, 2022). "This is already known for the case of lung adenocarcinoma with EGFR mutations." (PMID 36077736, 2022). "For lung adenocarcinoma patients in East Asia, 40%–60% of them were EGFR mutation positive." (PMID 34766737, 2022). "In addition, a recent study revealed that the EGFR variant allele frequency (EGFR-aVAF) of tumor tissue can predict the benefit of TKI treatment in advanced lung adenocarcinoma." (PMID 35053473, 2022). "Interestingly, four of these cases were lung adenocarcinoma cases, and all of them bared EGFR mutations (L858R missense mutations and in-frame indels) as the driver mutation." (PMID 35710642, 2022). "EGFR mutations are strongly associated with clinical outcomes in patients with lung adenocarcinoma." (PMID 36292235, 2022). "Therefore, EGFR gene mutations have been identified as a dominant driver in the tumorigenesis of GGN lung adenocarcinoma." (PMID 36059824, 2022). "Lung adenocarcinoma is the major cancer type that benefits from molecular targeted therapies, including tyrosine kinase inhibitors targeting the epidermal growth factor receptor (EGFR) mutations or ALK, EMAP-like 4, and neurotrophic receptor tyrosine kinase fusions." (PMID 36397035, 2022). "We reported a novel EGFR exon 21 indel mutation in a lung adenocarcinoma patient." (PMID 36042660, 2022). "In addition, when applied in a clinical validation study with 30 lung adenocarcinoma patients harboring epidermal growth factor receptor (EGFR) mutations, the system successfully isolated the full spectrum of CTCs." (PMID 35664056, 2022). "Furthermore, Hsp90 inhibition is effective against murine lung adenocarcinomas driven by the L858R, the equivalent L597R mutation of EGFR." (PMID 35883461, 2022). "However, the role of GPER1, a novel G-protein-coupled estrogen receptor, in the estrogen signaling pathway and the association between its expression and EGFR mutation in lung adenocarcinoma are less well understood." (PMID 35664735, 2022). "The use of epidermal growth factor receptor (EGFR) tyrosine kinase inhibitors (TKIs) as first-line treatment in patients with lung adenocarcinoma (LUAD) harboring EGFR-activating mutations has resulted in a dramatic improvement in the management of the disease." (PMID 35203491, 2022). "Female patients with lung adenocarcinoma have a high frequency of EGFR mutations." (PMID 35747829, 2022). "Furthermore, our previous study showed that PD-L1 expression level was associated with the frequency of primary resistance to EGFR-TKIs in treatment naïve advanced lung adenocarcinoma patients with EGFR mutation." (PMID 35697720, 2022).
lung adenocarcinoma (continued). "The data of all patients with lung adenocarcinoma referred to the Molecular Department of Masih Daneshvari Hospital Laboratory (National Research Institute of Tuberculosis and Lung Diseases) from 2014 to 2019 for EGFR mutation tests were collected." (PMID 35463723, 2022). "Based on the literature review, the current study accesses the systemic inflammation indices and clinical features associated with the TKI treatment-related toxicities and survival outcomes of EGFR-mutated lung adenocarcinoma patients receiving first-line TKI therapy." (PMID 35330404, 2022). "Moreover, although EGFR mutations are strongly associated with clinical outcomes in patients with lung adenocarcinoma, the effect of EGFR mutation status on prognosis is still unclear." (PMID 35330451, 2022). "We report a case simultaneously involving mGGNs and lung adenocarcinoma harboring primary EGFR-T790M mutation, in which the patient underwent the radical resection of lesions in the left upper lung, and continued the osimertinib treatment for the residual mGGNs in all lobes of the right lung." (PMID 36536456, 2022). "The odds ratios for lung adenocarcinoma with the EGFR Q787Q polymorphismwere 1.44 (95% CI=1.13-1.85; p=0.004), 1.75 (95% CI=1.21-2.51; p=0.003), and 1.27 (95% CI=0.93-1.73; p=0.14) for all patients, EGFR wild-type and EGFR-mutated lung adenocarcinoma, respectively." (PMID 35387120, 2022). "Finally, we retrospectively analyzed the prevalence of EGFR Q787Q polymorphism in stage IV lung adenocarcinoma and its association with the outcome of lung adeno-carcinoma patients treated with TKIs." (PMID 35387120, 2022). "With the advance of precision medicine and personalized treatments, targeted therapy of NSCLC plays an increasingly important role as a rising star and was demonstrated to effectively improve the survival prognosis of lung adenocarcinoma patients with EGFR gene mutations." (PMID 35800046, 2022). "Furthermore, we correlated HPV 16E6/18E6 expression and differentially localized EGFR expression with the clinical association and survival impact in lung adenocarcinoma patients." (PMID 36358752, 2022). "Moreover, Kutsuzawa (2020) study showed that lung adenocarcinoma patients harboring both G719X and S768I mutations of the EGFR gene can be successfully treated with afatinib and had PFS for 17 long months." (PMID 35606799, 2022). "EGFR mutations have been detected in 40–50% of lung adenocarcinomas." (PMID 35309168, 2022). "The aim of this study was to analyze clinicopathological prognostic factors for RFS after complete resection for pathologic stage IB-IIIA primary lung adenocarcinoma according to EGFR mutation status and to obtain basic knowledge on the selection of patients who should receive adjuvant therapy." (PMID 36085020, 2022). "Among Asians diagnosed with lung adenocarcinoma, approximately 50–60% of patients harbor an EGFR mutation and could benefit from EGFR-tyrosine kinase inhibitor (TKI) therapy." (PMID 35740489, 2022). "Patients with EGFR mutated lung adenocarcinoma could achieve a longer progression-free survival (PFS) from EGFR-TKIs than conventional chemotherapy." (PMID 35250988, 2022). "However, a study conducted recently showed that giving a low dose of erlotinib results in an EGFR T790M mutation on exon 20, which, as a consequence, causes resistance against EGFRTKIs in patients with lung adenocarcinoma." (PMID 36558926, 2022). "CSF could be a potential candidate for the genetic profiling of LM-LUAD, demonstrating the genetic characteristics of LM in EGFR-mutated lung adenocarcinoma on diverse EGFR-TKI therapies." (PMID 35614407, 2022). "This risk-scoring model may be clinically helpful in tailoring treatment strategies for patients with advanced EGFR-mutated lung adenocarcinoma." (PMID 35053473, 2022). "A number of studies had evaluated the association between EGFR and lung adenocarcinoma previously." (PMID 36011604, 2022).